SIRT1 (sirtuin 1)
Diseases named in the same sentence as SIRT1 in open-access papers (continued):
Sharing a sentence is not in itself a finding about the gene and the disease.
diabetes (continued). "In addition, in the setting of diabetes, the endothelium-specific transgenic overexpression of SIRT1 in mice reduced p66Shc expression at both the mRNA and protein levels compared with wild-type diabetic mice." (PMID 30918103, 2019). "In addition to finding that Epac1 and glycyrrhizin can both protect the retina against diabetes-induced damage, we also unexpectedly observed that glycyrrhizin reduced SIRT1 levels in the retina of Epac1 mice, as well as in C57BL/6 mice." (PMID 31159195, 2019). "A number of models of diabetes have been used to evaluate the renoprotective effects of sirtuin-1, including both T1DM and T2DM models, such as the db/db diabetic mouse, streptozotocin (STZ) alone diabetic mouse/rat model, or a combination of STZ- and high-fat diet–induced diabetic mouse/rat models." (PMID 30707256, 2019). "Whether SIRT1 is taken part in diabetes-induced neuronal apoptosis and thus involve in the development of diabetic cognitive impairment is still not clear." (PMID 29892266, 2018). "Moreover, genetic polymorphisms of SIRT1 and SIRT2 have been reported to associate with diabetes development." (PMID 30559718, 2018). "Since SIRT1 and Nrf2 are pivotal regulators in diabetes mellitus patients suffering from MI/R injury, we hypothesized that HKL ameliorates diabetic MI/R injury via the SIRT1-Nrf2 signaling pathway." (PMID 29675132, 2018). "The major aim of our work was to explore whether SIRT1 is involved in neuronal apoptosis induced by diabetes." (PMID 29892266, 2018). "Moreover, in this study we aimed to determine the expression of inflammatory cytokines, oxidative stress factors, SIRT1, and of the cardiovascular parameters in obese patients with pre-diabetes vs. obese patients with normo-glycemic condition." (PMID 30246793, 2018). "Taken together, these findings are particularly important, as they indicate the relevance of diabetes-related gene expression pattern and pathways related to leukocyte SIRT1 overexpression in GDM and thereby provide insight into the transcriptomics of leukocytes in diabetic pregnancy." (PMID 30513672, 2018). "In support of our results, it has been reported that treatment with other ARBs, such as telmisartan and valsartan, increased the expression of SIRT1 in skeletal muscle cells of obese db/db mice and in myocardial cells of type-2 diabetes mellitus mice, respectively." (PMID 28146117, 2017). "Furthermore, SIRT1 overexpression has been also shown to be protective in diabetes-induced renal and retinal injury in diabetic mice, through attenuated p300, endothelin-1 (ET-1), and TGF-β1 expression." (PMID 29085333, 2017). "We were the first group to report that the SIRT1 activator resveratrol activates AMP-activated protein kinase (AMPK) (Diabetes 2005; 54: A383), and we think that the variability of this cascade may be responsible for the inconsistency of resveratrol’s effects." (PMID 28708087, 2017). "Targets for SIRT1 mediated deacetylation include a broad range of transcription factors and co-activators governing many central metabolic pathways, and several different models of SIRT1 over-expression in transgenic mice were shown to prevent diabetes." (PMID 29257069, 2017). "Deleting Sirt1 in proximal tubules accelerates diabetes-induced proteinuria." (PMID 28351995, 2017). "Furthermore, SIRT1 overexpressing mice were protected against the age-related development of diabetes and had a lower incidence of cancer." (PMID 29264533, 2017). "Our findings suggest that SIRT1 might be a potential therapeutic target for the treatment of cognitive impairment induced by type 2 diabetes mellitus." (PMID 29164153, 2017). "For instance, overexpression of SIRT1 reduces diabetes-exacerbated myocardial ischemia-reperfusion injury and oxidative stress via activating eNOS in diabetic rats, and the vasculoprotective effect of insulin after arterial injury is mediated by an eNOS-dependent mechanism." (PMID 26879172, 2016).
diabetes (continued). "Moreover, SIRT1 activation reduced diabetes symptoms and insulin secretion and delayed the onset of insulin resistance in diabetic rats." (PMID 27123454, 2016). "However, overexpression of silent information regulator 1 (SIRT1) reduces diabetes-exacerbated injury of myocardial ischemia and reperfusion and oxidative stress." (PMID 27067643, 2016). "Dysfunction of SIRT1 may contribute to abnormal cancer metabolism, cancer stemness, neurological disorders, obesity, and diabetes." (PMID 27379253, 2016). "To show whether the anti-apoptotic effect of anthocyanins is AMPK-dependent in diabetes, we performed additional experiments using siRNAs for AMPKΑ1, AMPKΑ2, and SIRT1 in cultured HGECs." (PMID 26116070, 2015). "However, the expression of Nampt and Sirt1 in gastric cancer with diabetes remains to be elucidated." (PMID 25815791, 2015). "Interestingly, these detrimental changes were blunted in SIRT1 overexpressing transgenic mice with diabetes." (PMID 25753689, 2015). "It is also possible that SIRT1 may influence several other inflammatory cytokines which are of importance in the context of nephropathy and retinopathy and other chronic diabetic complications." (PMID 25753689, 2015). "Irrespective of various categories such as differences in age (>60), sex, diabetes mellitus, hypertension, and number of comorbidities, the SIRT1 and SIRT3 levels were still significantly lower in case of frail as compared to nonfrail; however, in case of SIRT2, the differences were not significant." (PMID 25100619, 2014). "Interestingly, proximal tubular cell-specific Sirt1 transgenic mice showed a resistance to diabetes-related progression of podocyte damage and subsequent proteinuria." (PMID 25126552, 2014). "Due to a research of Spiegelman as he mentioned, the pancreas activation of SIRT1 can increase the pancreas insulin secretion, resulting in gluconeogenesis in the liver, which may treat diabetes adversely." (PMID 25386563, 2014). "Hyperglycemia decreases SIRT1 expression in cultured endothelial cells, whereas overexpression of SIRT1 prevents the hyperglycemia-induced vascular cell senescence and thereby protects against vascular dysfunction in mice with diabetes." (PMID 23734259, 2013). "Therefore, we investigated the regulation of SIRT1 in cultured VSMCs under various stress conditions including diabetes." (PMID 23734259, 2013). "Given increasing interests of SIRT1 in many biological processes including cancer, aging, diabetes, and neuronal diseases, YK-3-237 may represent a valuable tool for basic research and pharmaceutical development." (PMID 23846322, 2013). "In addition to antioxidant effects, resveratrol has other propertiesthat can ameliorate diabetes or high glucose-induced kidneyinjurybyactivating AMPK or SIRT1." (PMID 24379901, 2013). "Therefore, Sirt1 activators have been suggested as therapeutic targets for insulin resistance, diabetes and metabolic disease." (PMID 22913271, 2012). "SIRT1 activation prevents endothelial senescence during hyperglycemia, blocks atherosclerotic lesions during elevated lipid states, modulates adipocyte differentiation, and prevents endothelial cell apoptosis during experimental diabetes." (PMID 23203037, 2012). "This suggested that inhibition of hepatic SirT1 could be a potential method to treat type 2 diabetes mellitus." (PMID 23316227, 2012). "Studies investigating the role of SIRT1 in diabetes and skeletal muscle are limited." (PMID 22203837, 2012). "Efforts to increase Sirt1 activity by resveratrol treatment or to increase Sirt1 expression in transgenic mice by knockin or over expression of a bacterial artificial chromosome containing a Sirt1 transgene have been shown to improve glycemic response in murine models of diabetes mellitus." (PMID 21858169, 2011).
diabetes (continued). "Some interactions with a nominal p≤0.01 were found between sex and SNPs in the UCP1 and UCP3 gene; between smoking, diabetes, hypertension and SNPs in UCP5 and SIRT5; and between SNPs in the UCP5 gene and the UCP1, SIRT1, SIRT3, SIRT5, and SIRT6 genes in association with plaque phenotypes." (PMID 22087257, 2011). "Inparticular, old Sirt1-tg mice are partially protected from diabetes,osteoporosis and cancer." (PMID 20562473, 2010). "Together, this suggests that SIRT1 activation could be a new diabetes treatment strategy." (PMID 41304967, 2025). "The Cdk5-NGF/Sirt1 axis may be a new target for the treatment of diabetes." (PMID 41181709, 2025). "Fifth, the impact of SIRT1 should also be investigated in non-DM models to better understand its effects in populations without diabetes." (PMID 39636756, 2025). "In addition, low-AGE diets have been connected to reductions in inflammatory markers, 8-isoprostane, leptin, circulating AGE levels, RAGE, as well as to increased adiponectin levels and mononuclear cells sirtuin-1 in healthy subjects and patients with diabetes." (PMID 39518960, 2024). "Hence, SRT2104 may beneficially influence central neuropathy in diabetes by ameliorating hippocampal dendritic alterations and enhancing cognitive function, mediated by SIRT1 activation and modulation of related signaling pathways." (PMID 38448466, 2024). "Additionally, in a streptozotocin-induced diabetes mouse model, tetrahydrocurcumin enhanced cardiac parameters, reduced myocardial fibrosis and cardiac hypertrophy, diminished ROS generation, and elevated SIRT1 expression." (PMID 37630770, 2023). "However, overexpression of Sirt1 attenuated diabetes-induced decrease in Mfn2 activity." (PMID 37415667, 2023). "In addition, diabetes decreases autophagosome formation and mitophagy in the retinal mitochondria, and Sirt1 overexpression ameliorates this, further strengthening the role of Mfn2 activation in the mitochondrial dynamic and removal of the damaged mitochondria in diabetic retinopathy." (PMID 37415667, 2023). "Furthermore, Sirt1 overexpressing mouse model, the model which is protected from the development of diabetic retinopathy and retinal mitochondrial damage, is also protected from diabetes-induced increase in Mfn2 acetylation and decrease in its GTPase activity." (PMID 37415667, 2023). "Moreover, Sirt1 activity is inhibited in diabetes and its expression is downregulated, and mice overexpressing Sirt1 are protected from diabetes-induced retinal mitochondrial damage, vascular dysfunction and the development of histopathology characteristic of diabetic retinopathy." (PMID 37415667, 2023). "Moreover, the mechanism revealed here for SIRT1 activation by 1,25(OH)2D3 may be relevant for diseases associated with VD deficiency beyond CRC, including autoimmune disorders and diabetes." (PMID 37530744, 2023). "Understanding the function of the SIRT1-AMPK pathway in diabetes and elucidating the regulatory impact of those on fatty acids, as well as the effect of the medicine on modifying the level of fatty acids through the SIRT1-AMPK route, is the primary objective of this study." (PMID 37534224, 2023). "In addition to its effects strictly exerted in response to DNA damage, SIRT1 induces an increase in lifespan by protecting against the onset of age-related diseases such as diabetes mellitus, hepatic steatosis, cardiovascular diseases, atherosclerosis, osteoporosis, and neurodegenerative disorders." (PMID 35956321, 2022). "Therefore, deregulation of SIRT1 functions may induce tissue-specific degenerative processes, thus leading to various human pathologies, including cancer, diabetes, and cardiovascular diseases such as myocardial ischemia/reperfusion injury." (PMID 36235072, 2022).
diabetes (continued). "The occurrence of diabetes can lead to a decrease in SIRT1 activity and its expression, and then the enhanced acetylation of FOXO1 will lead to a significant increase in blood glucose in vivo after FOXO1 activation, which may ultimately aggravate insulin resistance." (PMID 35739982, 2022). "The decrease in SIRT1 levels in HIV patients may be of clinical relevance for the pathogenesis of various comorbidities such as the activation of astrocytes in HIV-associated neurocognitive disorder and the onset of diabetes-related chronic kidney disease." (PMID 35159154, 2022). "SIRT1 possess beneficial effects against aging-related diseases such as Alzheimer’s disease (AD), Parkinson’s disease (PD), Huntington’s disease (HD), Depression, Osteoporosis, Myocardial ischemia (M/I) and reperfusion (MI/R), Atherosclerosis (AS), and Diabetes." (PMID 35935939, 2022). "Therefore, a decrease in PGC-1α activity and mitochondrial dysfunction in the pathophysiology of diabetes-related renal impairment may be attributed to changes in the AMPK/SIRT1 pathways." (PMID 36262282, 2022). "In addition, SIRT1 prevents diabetes by reducing oxidative stress and inflammation." (PMID 34656137, 2021). "Overall, the findings of our research suggested that suppression of miR-383 repressed oxidative stress and reinforced the activity of endothelial cells by upregulation of SIRT1 in db/db mice, and targeting miR-383 might be promising for effective treatment of diabetes." (PMID 31994599, 2020). "The involvement of SIRT1 in diabetic vascular complications has increased, and the diverse mechanisms of SIRT1 against oxidative stress gradually emerges, suggesting that modulation of SIRT1 activity may be an available therapeutic intervention against diabetes-induced vascular diseases." (PMID 33304318, 2020). "Therefore, we investigated whether LBE has ameliorating effects on renal damage by suppressing NLRP3 inflammasome-related hyperinflammation and activating AMPK/SIRT1/PGC-1α signaling in type 2 diabetes mellitus (T2DM) mice." (PMID 32050658, 2020). "Also, it is certainly possible that PRR may directly regulating AMPK and SIRT-1 in diabetes and in high-glucose induced cells." (PMID 31800607, 2019). "We used DKD models, such as the streptozotocin-induced diabetes mellitus model and db/db mice, to demonstrate the corruption of proximal tubule–podocyte interaction including a reduction in proximal tubular SIRT1 levels concomitant with decreased SIRT1 and increased claudin-1 in podocytes." (PMID 30859351, 2019). "Moreover, it has been shown that reduced SIRT1 expression and activity may lead to diabetes in mice and humans." (PMID 30736780, 2019). "In addition, upregulation of sirtuin-1 attenuates DN in various experimental models of diabetes and in renal cells, including podocytes, mesangial cells, and renal proximal tubular cells, incubated with high concentrations of glucose or advanced glycation end products." (PMID 30707256, 2019). "While EX527 reversed the changes of Nrf2 and HO-1 induced by SIRT1, suggesting melatonin could protect kidney against I/R injury in diabetes by up-regulating the expression of the SIRT1 protein, which then consequently activates Nrf2 and induce HO-1 expression." (PMID 30578379, 2019). "It has been shown that SIRT1 attenuates oxidative stress in coronary arterial endothelial cells exposed to elevated glucose levels and in rats with streptozotocin-induced diabetes; therefore, SIRT1 may exert protective effects against diabetes and its complications." (PMID 30736780, 2019).
diabetes (continued). "Since GDM and T2DM share an underlying pathophysiology, suggesting that a striking parallel may exist between these two diseases on the genetic level, the following stages went on to investigate specific changes in diabetes-relevant genes in the leukocytes of GDM patients with SIRT1 overexpression." (PMID 30513672, 2018). "Therefore, we aimed to investigate whether rescue of SIRT-1 expression/activation could influence diabetes-related oxidative stress via H3K56 deacetylation." (PMID 29330620, 2018). "Finally, low Sirt1 and Sirt3 expression, due to high NADH/NAD, may decrease Foxo-1 and MnSod expression, causing oxidative stress that results in cell death/aging or diabetes." (PMID 26558285, 2015). "Whether SIRT1 regulates autophagy in diabetes remains elusive." (PMID 24889822, 2014). "In conclusion, the present study shows that previous diabetes induction in vivo negatively regulated SIRT1 amounts in rat VSMCs, consistent with the in vitro effects of high glucose concentrations, whereas we were unable to demonstrate SIRT1 modulation by TNF-α." (PMID 23734259, 2013). "Studying the role of SIRT1 in non-DM models could provide valuable insights into its broader implications, independent of diabetes-related pathways." (PMID 39636756, 2025). "In diabetes, vanillic acid shows favorable properties by activating the AMPK/Sirt1/PGC-1α pathway, modulating insulin signaling pathways such as Akt and ERK1/2, and regulating enzymes and proteins involved in glucose and lipid metabolism." (PMID 39850111, 2025). "Recent studies indicate that adipokines, lipokines, or microRNAs secreted from brown adipose tissue can protect kidney function in diabetes, involving the activation of the renal AMP-activated protein kinase/sirtuin 1/PGC1α signaling pathway." (PMID 41369384, 2025). "The pathway enables a multifaceted diabetes intervention by simultaneously improving insulin signaling (AMPK‐dependent), normalizing metabolic flux (SIRT1‐mediated), and restoring mitochondrial function (PGC‐1α‐driven)." (PMID 41268687, 2025). "Factors such as aging, oxidative stress, hypertension, diabetes, and obesity can significantly deplete NAD+ levels, impairing SIRT1′s anti‐inflammatory functions." (PMID 41416347, 2025). "The SIRT1/FOXO1 signalling pathway is involved in the regulation of a variety of physiological processes, and SIRT1 can play a synergistic role in attenuating diabetes‐induced renal injury through FOXO1‐mediated oxidative stress and autophagy together." (PMID 40008520, 2025). "Additionally, we evaluated potential correlations between SIRT1 levels and peritoneal membrane function (assessed by the Kt/V index), demographic characteristics, clinical parameters, comorbidities such as cardiovascular disease and diabetes, and pharmacological treatments." (PMID 41009597, 2025). "SIRT1 provides organ protection by modifying FOXO1/PGC‐1α to strengthen antioxidant defenses, relieving nerve damage in diabetes, and reducing kidney scarring by blocking TGF‐β signals." (PMID 41268687, 2025). "The spectrum of SIRT1 activity makes it a significant contributor to the development of cardiovascular disease, chronic kidney disease (CKD), and diabetes." (PMID 41009597, 2025). "After adjusting for age, BMI, and diabetes duration in the multivariable model, CD38, NAMPT, and SIRT1 remained strong independent predictors of albuminuria, confirming that their associations were not confounded by these clinical covariates." (PMID 41470091, 2025). "As SGLT2 inhibitors activate sirtuin 1 (and thus PGC-1α and FGF21), they are more cardioprotective than other diabetes medications." (PMID 41155523, 2025).